EGFR (epidermal growth factor receptor)
Diseases named in the same sentence as EGFR in open-access papers (continued):
Sharing a sentence is not in itself a finding about the gene and the disease.
cancer (continued). "These activating mutations can be found either in anti-EGFR agents’ naive cancers (primary resistance) or as a consequence to the exposure of the malignancy to such agents (acquired resistance)." (PMID 30691487, 2019). "EGFR over-expression is implicated in various types of cancer such as breast, colon, ovarian and prostate through enhancing the cancer cell proliferation, invasiveness, metastasis and angiogenesis." (PMID 30919701, 2019). "A substantial body of subsequent work has since shown that EGFR is frequently hyperactivated in human cancers via mutation and/or overexpression." (PMID 30959819, 2019). "Many studies have shown that NSCLC is characterized by high malignancy compared with other cancers, which is closely associated with high expression of EGFR signaling pathway in NSCLC7,8." (PMID 31296849, 2019). "EGF and Epiregulin (a member of the EGF family) can function as a ligand of epidermal growth factor receptor (EGFR) and activate EGFR signaling, which will promote multiple biological consequences associated with cancer development." (PMID 31695034, 2019). "Both the AKT and ERK signaling pathways are known to be downstream targets of EGFR, and EGFR activating mutations have been reported to deregulate these pathways in cancer." (PMID 30876460, 2019). "EGFR was the most commonly mutated cancer gene in this cohort occurring in 40.7% of AIS, 29.6% of MIA and 46.2% of ADC lesions." (PMID 31278276, 2019). "An activating EGFR mutation (EGFRm) is one of the main driver causes of oncogenesis for various cancers, including NSCLC." (PMID 31367332, 2019). "Overexpression of EGFR is associated with an increase in cancer cell survival, metastasis, invasion, resistance to chemotherapy, and poor prognosis." (PMID 31121829, 2019). "Primary cancers in all four patients were adenocarcinoma, and two of them had epidermal growth factor receptor (EGFR) driver mutation." (PMID 31389192, 2019). "The remaining EGFR variants transformed Ba/F3 cells and demonstrated similar doubling time to that of the parental cells provided IL‐3, indicating that these cancer‐derived variants are indeed EGFR activating mutations." (PMID 31314158, 2019). "Since EGFR signaling is implicated in the growth and progression of many cancers, a significant effort has been made to understand the full spectrum of its action in promoting cancer, thus informing the development of EGFR-targeted therapies." (PMID 31438559, 2019). "It was then demonstrated that in cancer cells a higher EGFR expression, together with the overexpression of the EGFR variant III (EGFRvIII), trigger the TF expression." (PMID 30949114, 2019). "Overall survival in patients, especially those with advanced cancer and EGFR mutations, was associated with plasma miR-195 levels and miR-122 expression." (PMID 30953094, 2019). "The immunogenicity of 40-mer long peptides containing the 11 Del19 mutations of EGFR as a component of cancer vaccine is currently being studied." (PMID 31722672, 2019). "The downregulation of EGFR is associated with the inhibition of cancer cell growth, invasion and metastasis." (PMID 30890933, 2019). "Overexpression of EGFR is associated with an increased risk of invasion or metastasis, while the inhibition of EGFR leads to decreased cancer cell division, migration, angiogenesis, and apoptosis in solid tumors." (PMID 30530570, 2019). "Consideration of the overactivation and crucial role of EGFR in most cancers, it was selected as the underlying downstream genes of miR-27a in cSCC cells." (PMID 32039029, 2019). "The development of cancer is closely related to the mutation and abnormal expression of proto-oncogenes such as epidermal growth factor receptor (EGFR)." (PMID 31367332, 2019).
cancer (continued). "In most cancers, especially in most epithelial tumors, EGFR is commonly upregulated and closely associated with poor differentiation or unfavorable prognosis." (PMID 32039029, 2019). "The VM26-promoted detachment of cancer cells, associated with depletion of EGFR, was particularly apparent with prolonged treatment." (PMID 31374910, 2019). "The EGFR portion contains two missense mutations (T790M–L858R) in the tyrosine kinase domain that have been identified in human cancers." (PMID 31198408, 2019). "It is associated with resistance to cancer treatments; for instance, Cetuximab and Gefitinib resistant cells have increased levels of nuclear EGFR." (PMID 31426451, 2019). "EGFR hyperactivity, caused either by mutation or overexpression of the ligand or receptor, contributes to a variety of human cancers." (PMID 31118055, 2019). "Positive results from pre-clinical studies prompted extensive clinical studies in NSCLC patients, which have demonstrated anti-cancer activity against EGFR mutated cancers." (PMID 30975211, 2019). "It is important to understand the mechanism underlying EGFR inhibitor-induced pruritus and skin toxicity to prevent premature termination of chemotherapy and to improve quality of life in cancer patients." (PMID 31835310, 2019). "Given lipid metabolic reprogramming is widely known as a hallmark of cancer and intimately linked with EGFR-stimulated cancer growth." (PMID 30876460, 2019). "We used the crystal structures of the EGFR, ErbB2, ErbB3, and ErbB4 kinases that constitute this family to perform rigidity decomposition and then align the positions of the predicted cancer driver mutations with the structural mobility maps." (PMID 31245384, 2019). "EGFRvIII is a ligand-independent, mutated form of the EGFR and its expression has been associated with poor prognosis in several human cancers." (PMID 30899442, 2019). "Cutaneous ADRs in both EGFR and PD-1 inhibitors have been reported to be associated with cancer response to therapy, highlighting the clinical utility of early detection." (PMID 31162134, 2019). "Most of the molecular-targeted drugs used in the treatment of NSCLC inhibit specific targets that induce cancer evolution [so-called “oncogenic drivers (i.e., EGFR mutation, ALK translocation, ROS1 translocation, and BRAF mutation)”]." (PMID 31049758, 2019). "In human cancers, tyrosine kinases of the epidermal growth factor receptor (EGFR) family are frequently mutated." (PMID 31223315, 2019). "Database analysis revealed that cancer cells carrying the resistance mutation in EGFR or MET amplification appear to depend on MTHFD2 for growth." (PMID 30532069, 2019). "This secondary kinase mutation results in a drug-resistant state of the cancer, where the actions of EGFR inhibitors are abrogated while its intrinsic EGFR kinase activity is maintained; this in turn contributes to ‘oncogenic drift’." (PMID 30700700, 2019). "While the majority of somatic mutations in the EGFR and ErbB2 kinases increase the kinase activity, a number of the classified ErbB4 cancer mutants have been shown to inhibit or reduce the kinase activity." (PMID 31245384, 2019). "It is also shown that cytosolic PKM2 is associated with Epidermal growth factor receptor (EGFR) expression and prolongs the protein half-life of EGFR in cancer cells by stabilizing EGFR-Heat shock protein 90 (HSP90) protein complex." (PMID 31120964, 2019). "Nevertheless, EGFR amplification and mutations have been shown to be responsible for many other cancer types." (PMID 30871102, 2019).
cancer (continued). "Curcumin is also able to interfere with the cell signaling pathway of EGFR, a family of receptor tyrosine kinases, that is reported to be associated with the proliferation, adhesion, migration, and differentiation of cancer cells." (PMID 31590362, 2019). "The over-expression and/or mutation of EGFR plays an important role in the growth of cancer including cell proliferation, anti-apoptosis, metastasis, and angiogenesis." (PMID 30769844, 2019). "Mutations resulting in EGFR overexpression have been shown to be associated with the progression of different types of cancer; therefore, targeting this protein has been an important issue in medicinal chemistry in recent decades." (PMID 31374910, 2019). "More than 25% of HNSCC tumors bear FAT1 mutation or deletion, approximately twice the frequency of EGFR alteration in this cancer type." (PMID 31817001, 2019). "Activation of the epidermal growth factor receptor (EGFR) pathway plays an important role in the progression of cancer and is associated with a poor prognosis in patients." (PMID 31615015, 2019). "EGFR is frequently found to be overexpressed in various cancers, and resistance to EGFR TKIs is associated with EGFR overexpression." (PMID 30791926, 2019). "Despite the initial benefits of EGFR inhibitors in cancer patients harboring EGFR mutations, the rapid development of acquired resistance (AR) is a major obstacle in clinical practice and often leads to therapeutic failure and disease recurrence." (PMID 30621238, 2019). "The epidermal growth factor receptor (EGFR) signaling pathway has been implicated in many human diseases, especially in cancer, as it plays a central role in regulating the survival, proliferation, migration, and differentiation of various tissues." (PMID 30735525, 2019). "A number of EGFR signaling pathways have been linked to NFκB activation downstream of ligand stimulation or constitutive EGFR activation in cancer cells, primarily by promoting degradation of IκB proteins that sequester inactive NFκB proteins in the cytoplasm." (PMID 31349602, 2019). "Another study has demonstrated that drug resistance to TKIs targeted to epidermal growth factor receptor is linked to maintenance of mutant EGFR in cancer cells with highly abundant copies of eccDNAs." (PMID 31285839, 2019). "The dual starvation for glutamine and EGF, resulting in the deficiency of ATP and the weakness of EGFR functions, accelerates and reinforces the autophagic protein degradation in cancer cells exposed to the compound VM26." (PMID 31374910, 2019). "Persistent activation of EGFR enables cancer cells to engage in autonomous proliferation, which is a critical hallmark of cancer." (PMID 31717697, 2019). "It has been demonstrated in cancer cells that EGFR is altered through various mechanisms, such as gain-of-function mutations, EGFR gene gain, and overexpression of ligands and receptors." (PMID 31200451, 2019). "EGFR mutations have been implicated in a number of human cancers, and anti-cancer drugs have been developed that aim to block EGFR signaling." (PMID 31164594, 2019). "Cancer‐associated kinase domain variants in the epidermal growth factor receptor (EGFR) are common in non‐small‐cell lung cancer (NSCLC) as they can result in the increased ligand‐independent kinase activity of the receptor." (PMID 31314158, 2019). "Tyrosine kinase inhibitors (TKIs) that control EGFR are very efficient in the treatment of cancers possessing EGFR mutations, with a characteristic therapeutic window." (PMID 30947315, 2019).
cancer (continued). "Together, these data support the scientific validity of our study design, which analyzed EGFR status as a model for a candidate genetic profile associated with cancer cell radiosensitivity as assessed by clonogenic assays." (PMID 31349558, 2019). "Cases of EGFRM+ NSCLC with poor response to EGFR-TKIs due to pre-treatment co-mutations in other cancer-drivers have been documented by several groups." (PMID 31266248, 2019). "More than 30 different RTKs have been implicated in cancer and epidermal growth factor receptor (EGFR) system has been reported to be the most prevalent deregulated RTKs which enables them to be chosen as a prototype for drug discovery target." (PMID 35582567, 2019). "Mutated epidermal growth factor receptor (EGFR) is one of the most successful targets in cancer targeted therapy." (PMID 31367332, 2019). "We analyzed the association between EGFR expression and ccRCC in 6 trials with 365 cancer tissues and 88 normal tissues." (PMID 30895194, 2019). "High expression levels of EGFR and ErbB2 has been implicated in the development of various types of cancers including breast, lung, colorectal, ovarian, prostate, head and neck." (PMID 30688116, 2019). "Nuclear localized EGFR has been associated with disease progression and worse overall survival in numerous cancers." (PMID 31314158, 2019). "Increased EGFR tyrosine kinase activity, due to over-expression and/or somatic mutation(s), has been linked to a variety of human cancers." (PMID 31536605, 2019). "The ctDNA sensitivity was similar to that reported for the detection of EGFR-activating mutations and it is commonly considered adequate for a cancer screening test." (PMID 30190486, 2018). "Conversely, high methylation levels would cause EGFR to be overexpressed and amplified, and are driving events in cancer." (PMID 29983747, 2018). "Small‐molecule targeted inhibitors and/or tyrosine kinase inhibitors were a breakthrough in the treatment of patients with advanced cancers with target oncogene mutations (e.g. epidermal growth factor receptor (EGFR) and Met)." (PMID 29575431, 2018). "We predicted that cancer lines with mutations in KRAS or EGFR would be more sensitive to the potential effects of BCI treatment on numbers of viable cells, since DUSP6 would be required to restrain the toxic effects of P-ERK in these cells." (PMID 30475204, 2018). "At present, molecular targeted therapies have been shown great success in NSCLC and other cancer types, the reprehensive and the most prosperous paradigm is by targeting mutation-activated epidermal growth factor receptor (EGFR) in NSCLC patients." (PMID 30425968, 2018). "EGFR is overexpressed, mutated, or dysregulated in numerous cancers and hence, is an attractive target for many malignancies." (PMID 29552283, 2018). "By contrast, GalNT1 can exhibit a mucin-independent function in cancer and be implicated in other pathways, such as EGFR signaling, by increasing EGFR degradation via decreasing of EGFR O-glycosylation." (PMID 30038662, 2018). "The aberrant activation of members of the family of epidermal growth factor receptor tyrosine kinases (EGFR/ERBB) has been implicated in cancer development and progression." (PMID 29515761, 2018). "A cancer study reported that CRIPTO1 was expressed in a certain type of non-small cell lung cancer that causes intrinsic resistance to specific inhibitors of EGFR tyrosine kinase activity and participates in EMT." (PMID 30670929, 2018). "Epidermal growth factor receptor (EGFR) is either amplified or mutated in a variety of cancers and contributes significantly to tumorigenesis (Chong and Jänne, 2013, Ciardiello and Tortora, 2008)." (PMID 30021161, 2018). "The Epidermal Growth Factor Receptor (EGRF; ErbB-1) is a member of the ErbB family of receptors, whose mutations have been identified as affecting ErbB-1 expression or activity and are associated with cancer." (PMID 30453677, 2018).
cancer (continued). "Inappropriate activation of the EGFR in cancer mainly results from amplification and point mutations at the genomic locus, but transcriptional upregulation or ligand overproduction due to autocrine/paracrine mechanisms has also been described." (PMID 29124875, 2018). "In conclusion, the vast majority of advanced EGFR-mutated NSCLCs in our cohort showed co-mutations in other cancer driver genes before receiving first-line erlotinib-treatment." (PMID 29899852, 2018). "One strategy to target cancer specific proteins is with inhibitors that target the mutant variant of the protein: drugs such as gefitinib (against mutant EGFR) and vemurafenib (against BRAF V600E) have a good degree of success in cancer management." (PMID 30150714, 2018). "Mutations in cancer related genes, including Akt1 and EGFR, and intratumoral heterogeneity can induce chemotherapy resistance." (PMID 30111862, 2018). "Epidermal growth factor receptor (EGFR) upregulation is associated with enhanced proliferation and drug resistance in a number of cancers." (PMID 29682209, 2018). "EGFR signaling pathways maintain their activity even in EGFR TKI-resistant cancers caused by hyper-activated MET signaling." (PMID 30404198, 2018). "EGFR is involved in cell proliferation, differentiation, and survival and is often overexpressed, amplified, or mutated in a number of different cancers." (PMID 29464066, 2018). "Based on the outcome of these analyses, we selected two cancer-associated PTMs for in-depth study: S768, located in the protein kinase domain of EGFR, and S661/S695 located in the PKC terminal domains of PKCβ and PKCθ, respectively." (PMID 29695735, 2018). "PI3K/Akt is one of the pathways stimulated by radiation that is known to be involved in the inhibition of cell death via apoptosis; further, several studies have also linked overexpression and activation of EGFR with radiation resistance in cancer." (PMID 29439394, 2018). "Though EGFR is implicated in many cancer types and is a target for many anti-cancer therapies, this risk locus has not been previously associated with any other cancer type." (PMID 29743610, 2018). "Oncogenic membrane receptor tyrosine kinases such as MET and EGFR, or auto-active variants thereof, are important targets for cancer precision therapy." (PMID 29728634, 2018). "EGFR-tyrosine kinase inhibitors, such as Erlotinib, have shown some success with EGFR+ or EGFR mutated cancers, however resistance can occur over time." (PMID 30086763, 2018). "STAT3 is frequently found activated in several cancers including EGFR wild type as well as EGFR-mutated NSCLC." (PMID 29576846, 2018). "Mutations that affect EGFR overexpression or upregulation correlate with several cancers, including UCB." (PMID 29135410, 2018). "Enrichment analysis of KEGG pathways and MsigDB C2 gene sets on human orthologs and their first degree binding partners identified MAPK signaling, Wnt, VEGF, TGFβ, or EGFR signaling pathways, all strongly implicated in cancer." (PMID 30325918, 2018). "No report has described the role of MPV in patients undergoing molecular targeted therapy in any type of cancer and EGFR mutation is the most common targetable oncogenic driver in NSCLC." (PMID 30192878, 2018). "EGFR mutations companion diagnostics have been proved to be crucial for the efficacy of tyrosine kinase inhibitor targeted cancer therapies." (PMID 30393665, 2018). "EGFR expression is found to be altered or the receptor is found to be mutated in several types of cancer, including lung, breast, head and neck and gastrointestinal tumors for example." (PMID 29455659, 2018). "Overexpression of EGFRs is typically observed in various cancer cells, and EGFR mutations lead to constitutive signaling." (PMID 30076305, 2018).